ST6GALNAC5 (ST6 N-acetylgalactosaminide alpha-2,6-sialyltransferase 5)
Description:
Predominantly catalyzes the biosynthesis of ganglioside GD1alpha from GM1b in the brain, by transferring the sialyl group (N-acetyl-alpha-neuraminyl or NeuAc) from CMP-NeuAc to the GalNAc residue on the NeuAc-alpha-2,3-Gal-beta-1,3-GalNAc sequence of GM1b. GD1alpha is a critical molecule in the communication and interaction between neuronal cells and their supportive cells, particularly in brain tissues, and functions as an adhesion molecule in the process of metastasis (By similarity). Also shows activity towards sialyl Lc4Cer (N-acetyl-alpha-neuraminosyl-(2->3)-beta-D-galactosyl- (1->3)-N-acetyl-beta-D-glucosaminyl-(1->3)-beta-D-galactosyl-(1->4)- beta-D-glucosyl-(1<->1')-N-acyl-sphing-4-enine) generating disialyl Lc4Cer, which can lead to the synthesis of disialyl Lewis a (Le(a)), suggested to be a cancer-associated antigen.
Synonyms: ST6GalNAcV; SIAT7-E; SIAT7E; MGC3184
Tractability: Antibody: UniProt predicts a signal peptide or a membrane-spanning region. PROTAC: its protein half-life has been measured.
Gene: Protein-coding gene on chromosome 1 (76,867,447 to 77,067,546, forward strand). Ensembl gene ENSG00000117069.
Subcellular location: Golgi apparatus membrane
Subcellular location (Human Protein Atlas): Vesicles
Pathways (Reactome):
Metabolism: Glycosphingolipid biosynthesis
Metabolism of proteins: Sialic acid metabolism
Gene Ontology:
Molecular function: alpha-N-acetylgalactosaminide alpha-2,6-sialyltransferase activity; sialyltransferase activity; alpha-N-acetylneuraminyl-2,3-beta-galactosyl-1,3-N-acetyl-galactosaminide 6-alpha-sialyltransferase activity
Biological process: ganglioside biosynthetic process; glycosphingolipid biosynthetic process; oligosaccharide biosynthetic process; oligosaccharide metabolic process; glycoprotein biosynthetic process
Cellular component: Golgi membrane
Genetic constraint (gnomAD): Loss-of-function variants: 26 observed, 32.14 expected, observed/expected ratio (o/e) 0.81, 90% interval 0.59 to 1.12. The upper end of that interval is the gene's LOEUF score, 1.12, which puts it in group 4 of 6, group 1 being the genes least tolerant of losing a copy. Missense variants: 427 observed, 467.23 expected, observed/expected ratio (o/e) 0.91, 90% interval 0.84 to 0.99. Synonymous variants: 194 observed, 177.17 expected, observed/expected ratio (o/e) 1.1, 90% interval 0.97 to 1.23.
Homologues: Orthologues: chimpanzee ST6GALNAC5 (99% identical), macaque ST6GALNAC5 (99% identical), pig ST6GALNAC5 (93% identical), rabbit ST6GALNAC5 (93% identical), dog ST6GALNAC5 (93% identical), mouse St6galnac5 (91% identical), rat St6galnac5 (91% identical), guinea pig ST6GALNAC5 (89% identical), tropical clawed frog st6galnac5 (71% identical), zebrafish st6galnac5a (65% identical), zebrafish st6galnac5b (59% identical). Paralogues in human: ST6GALNAC6 (42% identical), ST6GALNAC4 (38% identical), ST6GALNAC3 (32% identical), ST6GAL2 (20% identical), ST6GALNAC1 (20% identical), ST6GALNAC2 (19% identical), ST3GAL4 (18% identical), ST3GAL2 (17% identical), ST3GAL3 (17% identical), ST6GAL1 (17% identical), ST3GAL1 (16% identical), ST3GAL5 (15% identical), and 2 more.
Diseases named in the same sentence as ST6GALNAC5 in open-access papers:
ST6GALNAC5 is named in the same sentence as 19 diseases in open-access papers, as found by Europe PMC text mining. Sharing a sentence is not in itself a finding about the gene and the disease. The quoted sentences say what the papers report.
breast carcinoma (27 papers, 2012 to 2025). "ST6GALNAC5 is overexpressed in breast cancer cells and has been strongly linked to brain metastases." (PMID 32857815, 2020). "The ST6GALNAC5 gene that encodes an α2,6-sialyltransferase involved in the biosynthesis of α-series gangliosides, was previously identified as one of the genes that mediate breast cancer metastasis to the brain." (PMID 27529215, 2016). "In 2009 the gene ST6GalNAc5, was discovered over-expressed in breast cancer cells able to produce brain metastasis." (PMID 38279335, 2024). "The seventh cited paper was the only basic study in the 10 most cited papers, which anchored COX2, HBEGF, and ST6GALNAC5 as the key genes mediating breast cancer brain metastasis." (PMID 37091185, 2023). "The expression of ST6GalNAc5 in breast cancer cells enhances their ability to adhere to brain endothelial cells and breach the blood-brain barrier." (PMID 36497322, 2022). "ST6GalNAc5 and ST6Gal1, which mediate α2,6-sialylation, are upregulated in the brain metastasis process of breast cancer." (PMID 36497322, 2022). "Breast cancer cells infiltrated into the brain using a surface glycosylation α2,6-sialyltransferase ST6GALNAC5 to interact with and cross the BBB." (PMID 34222020, 2021). "Three genes, Cox2, HBEGF and ST6GALNAC5, identified by Bos and colleagues, were shown to promote transendothelial migration in breast cancer cell lines." (PMID 29784888, 2018). "We have shown that the expression of ST6GALNAC5 in MDA-MB-231 breast cancer cells resulted in the expression of GD1α ganglioside at the cell surface." (PMID 27529215, 2016). "In comparison with MCF-10A cells, the aggressive breast cancer cell line MDA-MB-231 showed an increased number of differentially expressed genes including ST6GALNAC5 (7.33-folds), ST8SIA4 (14.81-folds) and ST8SIA5 (3.11-folds)." (PMID 28032858, 2016). "The identification of ST6GALNAC5 as one of the genes involved in breast cancer brain metastasis raised the question of the capacity of breast cancer cells to synthesize α-series gangliosides." (PMID 25913930, 2015). "ST6GALNAC5 gene was also shown playing a role in HeLa cell adhesion and recently, ST6GALNAC5 was identified as one of the genes over-expressed in breast cancer cell populations selected for their ability to produce brain metastasis." (PMID 25913930, 2015). "Further analysis identified COX2, the epidermal growth factor receptor ligand HBEGF, and the α2,6-sialyltransferase ST6GALNAC5 as important determinants of transmigration of breast cancer cells through the BBB." (PMID 23344048, 2013). "Among the genes mapped to this deleted segment, the most relevant to cancer progression is probably ST6GALNAC5, a sialyltransferase recently reported to mediate breast cancer metastasis to the brain." (PMID 22314128, 2012). "Interestingly, the expression of the brain-specific ST6GalNAC5 enzyme by breast cancer cells was found to mediate brain metastases by enhancing blood–brain barrier crossing." (PMID 40806752, 2025). "Through its mechanism, YTHDF3 increases the translation of m6A-enriched transcripts associated with cerebral metastasis of breast cancer, such as ST6 N-Acetylgalactosaminide Alpha-2,6-Sialyltransferase 5 (ST6GALNAC5), Gap Junction Protein Alpha 1 (GJA1), and EGFR." (PMID 39342406, 2024). "YTHDF3 promotes the translation of m6A-modified mRNAs of breast cancer brain metastasis-associated genes (e.g., ST6GALNAC5, GJA1, and EGFR) by recruiting eIF3a and increasing the expression of the corresponding proteins, which ultimately affects the brain metastasis of breast cancer." (PMID 39440064, 2024). "In addition, the expression of ST6GALNAC5 was also required for epithelial-to-mesenchymal transition (EMT) of MDA-MB-231 breast cancer cells." (PMID 37468844, 2023). "Indeed, transfection of the human ST6GalNAc5 cDNA into a breast cancer cell line resulted in the expression of GD1α." (PMID 34975914, 2021).
breast carcinoma (continued). "Moreover, ST6GALNAC5 was demonstrated as the only gene specifically correlated with brain metastasis of breast cancer and up-regulated in human brain metastasis samples." (PMID 25913930, 2015). "Interestingly, HBEGF, together with two other genes, COX2 and ST6GALNAC5, mediate breast cancer cell passage through the blood-brain barrier." (PMID 24403051, 2014). "The most relevant gene in the affected region is ST6GALNAC5, a sialyltransferase recently identified as related to the development of breast cancer metastasis, suggesting a possible role for this gene in the development of the early-onset breast cancer in these patients." (PMID 23469205, 2013). "ST6GALNAC5 is a brain-specific sialyltransferase and may directly influence breast cancer cell adhesion to cerebral endothelial cells." (PMID 23344048, 2013). "Furthermore, the expression of ST6GALNAC5, presumably increasing the expression of α-series gangliosides in breast cancer cells could promote their capacity to form brain metastasis." (PMID 25913930, 2015). "For example, breast cancer cells express COX2, the EGFR ligand HBEGF, and the α2,6-sialyltransferase ST6GALNAC5, which facilitate their traversal across the BBB." (PMID 40076927, 2025). "Among these, the expression of ST6GALNAC5, ST8SIA3 and ST8SIA4 was significantly upregulated in breast cancer tissues compared with adjacent tissues, and ST8SIA2 and ST8SIA6 were upregulated in the adjacent tissues." (PMID 28032858, 2016). "As opposed, a more recent study showed that ST6GalNac5 overexpression in breast cancer cells leads to a decreased adhesion and no change in transmigration compared to controls in a human BBB model using CD34+ hematopoietic stem cell derived endothelial cells co-cultivated with brain pericytes." (PMID 34975914, 2021).
glioma (3 papers, 2012 to 2023). A benign or malignant brain and spinal cord tumor that arises from glial cells (astrocytes, oligodendrocytes, ependymal cells). "Similarly, glioma cells showed very low expression of ST6GALNAC5, which when overexpressed into U373 MG cells inhibited glioma growth in vivo." (PMID 33921986, 2021). "However, ST6GALNAC5 was found to be downregulated in glioma." (PMID 37468844, 2023).
breast tumors (2 papers, 2016 to 2022). "Target DEGs of miR-30c in our analysis were mostly related to the anti-apoptosis of abnormal tumor cells, including MAP3K9 in lung cancer, ST6GALNAC5 in prostate cancer, CSRNP3 in clear renal cell carcinoma, ZNF703 in breast tumors, and CLSPN in brain tumors." (PMID 36700234, 2022). "In the present work, we will analyse the expression of three genes of interest (PTGS2, HBEGF, and ST6GALNAC5) in the FFPE tissue of primary TN phenotype breast tumours with CNS metastasis compared to patients who do not present with cerebral metastasis." (PMID 27170832, 2016).
cervical cancer (2 papers, 2021 to 2024). A primary or metastatic malignant neoplasm involving the cervix. "They identified 6 genes as the best candidate methylated biomarkers of cervical cancer progression (RGS7, LHX8, ST6GALNAC5, TBX20, KCNA3 and ZSCAN18)." (PMID 34882728, 2021).
lung carcinoma (2 papers, 2022). "Overexpression of ST6GalNAc4 has been crucial for tumor cell glycosylation modification and lung cancer metastasis, although the roles of ST6GalNAc5 and ST6GalNAc6 in malignancies remain unclear." (PMID 36605200, 2022).
prostate carcinoma (2 papers, 2022 to 2023). A carcinoma that arises from epithelial cells of the prostate gland. "In this study, we found that overexpression of ST6GALNAC5 activated MAPK/ERK1/2 pathway in prostate cancer cells." (PMID 37468844, 2023).
colon cancer (1 paper, 2023). "ST6GALNAC5 is a glycosyltransferase that prevents cell death, and its overexpression in gastric cancer as well as in colon cancer was shown to inhibit apoptosis." (PMID 36675007, 2023).
colorectal cancer (1 paper, 2022). A primary or metastatic malignant neoplasm that affects the colon or rectum. "For example, in colorectal cancer, an increase in the expression of ST8SIA4, ST3GAL6, ST6GALNAC5 is associated with an increase in regulatory T cells and pro-tumoral M2 macrophages." (PMID 36009354, 2022).
epilepsy (1 paper, 2025). A brain disorder characterized by episodes of abnormally increased neuronal discharge resulting in transient episodes of sensory or motor neurological dysfunction, or psychic dysfunction. "In epilepsy, mapping our m6A-associated genes (e.g., PARP1, NBL1, RPL14) to their proteomic counterparts identified causal links to proteins such as ST6GALNAC5, CTNNA2, and TOM1L1, highlighting specific m6A-driven regulatory cascades at the protein level." (PMID 40624693, 2025).
meningioma (1 paper, 2021). A generally slow growing tumor attached to the dura mater. "In the malignant meningioma cell line, we observed changes in expression of sialyltransferases (ST3GAL1/2/3, ST6GALNAC5, and ST8SIA1) after glycation, which correlates with less aggressive behavior." (PMID 34943806, 2021).
metastatic tumors (1 paper, 2018). "Corresponding to the results that the two Neu5Ac-α-2,6- residues were necessary for these CSC HPs binding, the enzymes possibly catalyzing the sialylation reactions, ST6Gal1 and ST6GalNAc5, were found to be highly expressed in malignant and metastatic tumors and corresponding to a worse prognosis." (PMID 29755667, 2018).
pneumonitis (1 paper, 2022). An inflammatory process affecting the lung parenchyma. "Several of these filtered candidates were found to be secreted (C12orf49, COL10A1, FNDC4, ITLN2, MATN3, PDZD2, RS1, SCRG1, and ST6GALNAC5) making them potential candidate biomarkers useful for distinguishing IPF from pneumonitis." (PMID 35628257, 2022).
rectal cancer (1 paper, 2014). A primary or metastatic malignant neoplasm that affects the rectum. "Notably, many of these genes (ADRA1A, BARHL2, ERAS, ESRRG, RNF220 and ST6GALNAC5) are also targets of the Polycomb Repressor Complex-2, further supporting an important role of epigenetic crosstalk in controlling rectal cancer therapeutic responsiveness." (PMID 25261372, 2014).
cancer (12 papers, 2012 to 2026). A tumor composed of atypical neoplastic, often pleomorphic cells that invade other tissues. "The results showed that ST6GALNAC5 mRNA level was associated with the genesets related to cancer, cell cycle, Hedgehog signaling, neurotrophin signaling, ERBB signaling, and SNARE interaction." (PMID 37468844, 2023). "Another brain metastasis-specific gene, ST6GALNAC5, mediates the interaction of cancer cells with brain endothelial cells." (PMID 38714954, 2024). "These evidences suggest that the important role of ST6GALNAC5 in tumor metastasis, but promoting or inhibitory effect is highly dependent on cancer cell context." (PMID 37468844, 2023). "On the other hand, ASCL1 and ST6GALNAC5 have been described as protumorigenic in other cancer types." (PMID 30360578, 2018). "How ST6GALNAC5 is regulated in cancer development is under way." (PMID 37468844, 2023). "Lastly, ST6GALNAC5 was shown to promote BCBM by allowing adhesion and transmigration of cancer cells through the brain endothelium." (PMID 32645833, 2020). "Seven genes had variants found in the cancers of at least two ‘poor’ responders but in no 'good’ responders: ATRNL1, BAIAP2L2, ZNF384, ST6GALNAC5, ENSCAFG00000030179 (human ortholog: riboflavin kinase RFK), ENSCAFG00000029320, and ENSCAFG00000007370 (human ortholog: immunoglobin IGKV4-1)." (PMID 32857815, 2020). "Studies examining the molecular signature of brain-specific metastasis have identified α-2, 6-sialyltransferase ST6GALNAC5 (also known as α-N-acetylgalactosaminide), which is overexpressed in brain-trophic, but not in lung- or bone-trophic, metastasized cancer cells." (PMID 26883469, 2016).
tumor (7 papers, 2021 to 2026). "LGALS1, B4GALT6, and GALNT11 were upregulated and MGAT5, MAN1A1, MANBA, LUM, GALNT1 and 7, HAPLN3, and ST6GALNAC5 were downregulated in Fra-2 cl 1 select primary tumours, while MGAT4A was upregulated." (PMID 34693476, 2022). "The lipidomic analysis may be performed to further analyze the changes of various gangliosides in response to dysregulation of ST6GALNAC5 in the specific tumor cells." (PMID 37468844, 2023). "Since sialic acid plays vital roles in cell-cell communication, cell-matrix interaction, and adhesion, it was hypothesized that miR-182 might modulate sialylation via ST6GALNAC5, thus influencing cellular sialic acid in tumor cells." (PMID 34037099, 2021). "Our study proved that miR-182 participated in the proliferation and invasion of PCa cells via mediating expression of ST6GALNAC5 and established a miR-182/ST6GALNAC5/PI3K/AKT axis in regulation of tumor progression." (PMID 34037099, 2021).
ST6GALNAC5 also shares sentences with these, for which no sentence is quoted: brain tumors (1 paper); clear renal cell carcinoma (1); gastric cancer (1); glioblastoma (1).